BRCA1 (BRCA1 DNA repair associated)
Diseases named in the same sentence as BRCA1 in open-access papers (continued):
Sharing a sentence is not in itself a finding about the gene and the disease.
breast cancer (continued). "Deletions overlapping GTF2H2 are associated with decreased risk of breast cancer, suggesting that disruption of NER may be protective against the biological consequences of a BRCA1 pathogenic variant." (PMID 28145423, 2017). "A previous study reported a better prognosis in BRCA1 mutation carriers compared to non-carriers in patients with sporadic breast cancer." (PMID 29152070, 2017). "Based on their five and ten year figures for breast cancer free survival and overall survival after ovarian cancer, the authors suggest non-surgical management of breast cancer risk in women with a BRCA1/BRCA2-associated ovarian cancer." (PMID 28780755, 2017). "Nevertheless, surprisingly, PARP1 inhibition improves the therapeutic index of radiotherapy independent of breast cancer subtype or BRCA1 mutational status." (PMID 28978184, 2017). "Despite bilateral and early-onset breast cancer in the family, this patient tested negative for high-penetrance mutations in the BRCA1 and BRCA2 genes." (PMID 28241424, 2017). "Whether BRCA promoter methylation may occur as a second hit in BRCA1/2-related breast carcinomas is still unclear." (PMID 28569220, 2017). "Overall, BRCA1/2 genetic alterations may explain 10% of breast carcinomas arising in young women, but in studies from Arab countries much higher proportions have been reported." (PMID 29121898, 2017). "Peritoneal cancer was found less often in patients with BRCA1 mutation and breast cancer diagnosis before surgery than in patients without breast cancer prior to surgery – 1.18 % vs. 1.75 %." (PMID 26928677, 2016). "To reveal how relevant the BRCA1/NEAT1/miR-129-5p signaling axis is to breast cancer, we performed in silico analysis of publicly available cancer-related expression databases and published expression data to examine the expression correlation between these three molecules." (PMID 27556296, 2016). "The aim of our study is to compare the clinicopathological characteristics between Moroccan breast cancers associated or not with BRCA1 and BRCA2 mutations." (PMID 27129401, 2016). "Our results indicate that miR-498 regulates BRCA1 expression in breast cancer and its overexpression could contribute to the pathogenesis of sporadic TNBC via BRCA1 downregulation." (PMID 26933805, 2016). "Combined, these results suggest that FOXC1 is essential for BRCA1-mutant breast cancer cell growth and may predict sensitivity to treatment with olaparib in BRCA1-mutant cells, which warrants further validation using clinical samples." (PMID 27708239, 2016). "Common variants in 94 loci have been associated with breast cancer including 15 loci with genome-wide significant associations (P<5 × 10−8) with oestrogen receptor (ER)-negative breast cancer and BRCA1-associated breast cancer risk." (PMID 27117709, 2016). "Similarly, miR-182 downregulates BRCA1 expression in various breast cancer cell lines in vitro and in vivo, resulting in defective HR-mediated repair and increased sensitivity to irradiation and Olaparib." (PMID 27642590, 2016). "The GENESIS (GENE SISter) study was designed to identify new breast cancer susceptibility genes in women attending cancer genetics clinics and with no BRCA1/2 mutation." (PMID 26758370, 2016). "Breast cancer development in BRCA1/2 mutation carriers is a consequence of autonomous and nonautonomous cell factors, which serve as excellent targets for cancer prevention." (PMID 27072583, 2016). "Methylation of BRCA1 and 17βHSD-1 related to luminal A subtype of breast cancer." (PMID 27413552, 2016). "Interestingly, ectopic expression of LSD1 in basal-like breast cancer cells promoted downregulation of BRCA1 and hypersensitivity to Olaparib." (PMID 27642590, 2016). "BRCA1 promoter methylation is a frequent event in sporadic breast cancers." (PMID 27027444, 2016).
breast cancer (continued). "In this study, the cytotoxic potential of PB was evaluated in triple negative (ER, PR and Her2 negative), BRCA1 defective breast cancers since majority of the BRCA1 associated cancers belong to this category." (PMID 27220670, 2016). "Currently, BRCA1 or BRCA2 mutation carriers with breast cancer do not receive specific treatment targeting the defect in their tumor, despite strong preclinical and promising clinical evidence." (PMID 27323902, 2016). "Moreover, our in silico correlation analysis indicates that a significant portion of breast cancer cell lines (> 70%) manifested the regulation trend of the BRCA1/NEAT1/miR-129-5p axis." (PMID 27556296, 2016). "We found that loss of p16 transforms Brca1-deficient mammary epithelial cells and induces mammary tumors, though p16 loss alone is not sufficient to induce spontaneous mammary tumorigenesis." (PMID 27811360, 2016). "This could be important in breast cancer progression and contribute to the understanding of tumour suppressive role of BRCA1." (PMID 27043660, 2016). "It is necessary to study the BRCA1/2 genes involvement in the Algerian breast cancer occurrence." (PMID 26997744, 2016). "Whilst strongly associated with triple negative breast cancer, most young patients with this breast cancer subtype do not carry pathogenic BRCA1 mutations." (PMID 27087880, 2016). "Here we report that ALDH1 positivity could be one of the best markers for the identification of BCSCs from basal-like, BRCA1-defective breast cancer cell lines based on the isolation of putative CSCs followed by their in vitro mammosphere culture." (PMID 27229859, 2016). "Although hereditary tumors in women that carry BRCA1 mutations account for only a small percentage (5–10%) of breast cancers, the risk of developing the disease throughout the lifetime is much higher (up to 85%) in BRCA1 mutation carriers than in noncarriers." (PMID 27259235, 2016). "Of the 32 patients with BRCA1/2 negative result, four patients were found to have a variant of uncertain clinical significance; none of these patients had a personal history of breast cancer before the age of 35 years." (PMID 26997744, 2016). "Moreover, prophylactic salpingo-oophorectomy protects patients with breast cancer who are also BRCA1/BRCA2 carriers from developing ovarian cancer." (PMID 26928677, 2016). "Therefore, BRCA1 dysfunction is a significant factor underpinning the development of both hereditary and sporadic breast cancers." (PMID 27589844, 2016). "Additionally, we conducted a follow up of the patients for 98 months in order to assess the overall survival and disease free interval in BRCA1-methylated and unmethylated breast cancer patients." (PMID 27027444, 2016). "Moreover, breast cancer specific “Role of BRCA1 in DNA Damage Response” pathway was found to be differentially expressed, with the 2 different analyses highlighting similar molecular pathways." (PMID 27491308, 2016). "In summary, our study indicates that 2R/2R and 2R/1R were significantly associated with increased risk, and 1R/1R and 1R/0R were significantly associated with the decreased risk of BRCA1+ breast cancer, whereas 2R/1R was significantly associated with the increased risk of BRCA2+ breast cancer." (PMID 27148484, 2016). "In the second MRI study to evaluate BPE level and breast cancer odds, 23 women with a breast cancer diagnosed a median of 2 years after the index MRI and 23 age- and BRCA1/2 mutation status-matched women who did not develop breast cancer were included." (PMID 27552842, 2016). "BRCA1 and BRCA2 mutations account for 25–28% of hereditary breast cancers." (PMID 27899083, 2016). "Following Angelina Jolie’s announcement that she carried a genetic mutation that increased her odds of developing breast and ovarian cancer, referrals for genetic counseling and BRCA1/2 testing appeared to have increased the awareness of cancer, particularly for breast cancer." (PMID 27242959, 2016).
breast cancer (continued). "However, pathogenic mutations of BRCA1 and BRCA2 only explain 10–20% of breast cancers in patients with early-onset or a significant family history." (PMID 26824983, 2016). "EOC and breast cancer share some common risk factors (e.g. BRCA1/2 status); therefore, it might be expected that BNC2 has a role also in breast cancer onset." (PMID 27899818, 2016). "In total, all 4,520 non-BRCA1/2 breast cancer patients and 3,127 controls were genotyped." (PMID 27424772, 2016). "The increased risk of breast cancer in ATM carriers was then confirmed by direct ATM sequencing in breast cancer cases compared to controls and ATM is now considered a moderate-penetrance cancer susceptibility gene in BRCA1/2-negative patients with familial early-onset breast cancer." (PMID 27599564, 2016). "BRCA1 silencing in sporadic and hereditary tumors have been described in the last years to be a relevant mechanism associated to breast cancer progression in patients with no germline mutation." (PMID 26979459, 2016). "CBP/p300 up-regulates the level of the breast cancer specific gene BRCA-1." (PMID 26885691, 2016). "Despite the increased number of basal cells in BRCA1-mutation carriers, this study showed that the luminal cells, and not the basal cells, were the origins of basal-like breast cancer." (PMID 27110512, 2016). "Rs8051542 was found to be significantly associated with breast cancer risk in Tunisians and rs3112612 yielded moderate predictive power in Ashkenazi Jewish women with strong family histories but no identifiable BRCA1/2 mutation." (PMID 27486757, 2016). "The use of the three established methods for isolation of CSCs followed by in vitro self renewal analysis by mammosphere formation studies have thus brought out the ALDH1+ phenotype as the best candidate putative stem cell marker for BRCA1-defective breast cancer cells." (PMID 27229859, 2016). "The risk of CIA in young patients with breast cancer (≤47 years) does not appear to be related to BRCA1 or BRCA2 mutation status." (PMID 27234217, 2016). "Since BRCA1 mutation carriers are sensitive to PARP inhibitors, some LOX+ ER– breast cancer patients may also benefit from PARP inhibitors." (PMID 27147578, 2016). "Age at breast cancer diagnosis seems to have an effect on the BRCA1/2 detection rate." (PMID 26997744, 2016). "In the present study, we found that the frequency of BRCA1 and BRCA2 mutations was 23.3 % in our cohort of 133 Chinese women with familial breast/ovarian cancer, and the frequency of BRCA1 and BRCA2 mutations was 50 % in patients with a familial history of both breast cancer and ovarian cancer." (PMID 26852015, 2016). "BRCA1 and BRCA2 are the major genes associated with hereditary breast cancer susceptibility." (PMID 26997744, 2016). "We now went on to study if PB that has been shown to the selective to BRCA1-defective ovarian cancer cells could also selectively target BRCA1-defective basal-like breast cancer cells." (PMID 27229859, 2016). "To further affirm our results, we also investigated the correlation between BRCA1 mutation status and FOXO3 protein expression levels in human samples by immunohistochemical staining on tissue microarray constructed from 308 Korean breast cancer cases with known BRCA1 status." (PMID 27043660, 2016). "We employed a recently developed microchip platform to isolate BRCA1 protein assemblies natively formed in breast cancer cells with and without BRCA1 mutations." (PMID 27583302, 2016). "In this first Moroccan study comparing clinical and pathological characteristics of women carrying or not BRCA mutation, patients with BRCA1/2 mutation tend to develop early breast cancer with high-grade tumors." (PMID 27129401, 2016). "We found that p16 loss transformed Brca1-deficient mammary epithelial cells and induced mammary tumors, though p16 loss alone was not sufficient to induce mammary tumorigenesis." (PMID 27811360, 2016).
breast cancer (continued). "Germ-line mutations in BRCA1 and BRCA2 genes are associated with 5–10% of breast cancer incidence." (PMID 29138730, 2016). "Thus, our data indirectly confirmed that BRCA1 promoter hypermethylation was an early event of carcinogenesis in our breast cancer patients." (PMID 27027444, 2016). "In other studies, BRCA1 existed in even lower percentages, 9–32%, in sporadic breast cancer." (PMID 27413552, 2016). "The mean age at diagnosis of breast cancer and the mean age of first menarche was younger in BRCA1/2 mutation carriers than in non-carriers (p = 0.05)." (PMID 27129401, 2016). "In agreement, our ChIP assays showed that DNMT1/3a/3b and the transcriptional repressive histone mark H3K27me3 are recruited to the promoter region of FOXO3 in BRCA1-low and -mutated breast cancer cell lines but not in BRCA1-competent MCF-7 cells." (PMID 27043660, 2016). "We have previously shown that breast cancer cell lines show differences in the HR capacity although they share no common mutations in BRCA1 or BRCA2." (PMID 26799421, 2016). "We have earlier shown that Plumbagin (PB) can induce selective cytotoxicity to BRCA1 defective ovarian cancer cells; however, the effect of this molecule in BRCA1 mutated breast cancers has not been analyzed yet." (PMID 27220670, 2016). "While, our study indicated that in Iranian population, the breast cancer susceptibility is not randomly distributed but it is clustered in subset of BRCA1 alleles that can be identified by D17S855 and D17S1322 genotyping." (PMID 27351029, 2016). "The BRCA1 shortest transcript is highly expressed and efficiently translated in normal mammary glands, while the longer transcript is predominantly expressed in breast cancer tissues." (PMID 26824233, 2016). "Besides BRCA1 and BRCA2, inherited mutations in othertumor suppressor genes also increase the risk for breast cancer and other tumors." (PMID 27223485, 2016). "For example, Fackenthal and Olopade pointed out that mutations in 5’-UTR of BRCA1 and BRCA2 could predict the risk of breast cancer." (PMID 27649163, 2016). "Literature on the association of CENP-F immunohistochemical staining in breast cancer of patients with BRCA1 mutation is also lacking." (PMID 26868636, 2016). "Therefore, we screened germline VNTR polymorphisms in the XRCC5 promoter in three types of familial breast cancer (BRCA1+, BRCA2+, and BRCAx)." (PMID 27148484, 2016). "The aim of the present work is to evaluate the genomic profiles of a Chilean subset of hereditary breast cancer tumors by array-CGH, highlighting the different alterations found in tumors with loss of BRCA1 expression, and in tumors with germline BRCA mutations." (PMID 26979459, 2016). "We demonstrate for the first time that a naphthoquinone, PB selectively reduces the ALDH1+ population in basal-like BRCA1-defective breast cancer cells while enriching the ALDH1+ population in cancer cells harboring full length, functional BRCA1, the reason for which has to be analyzed in future." (PMID 27229859, 2016). "Several epidemiologic studies have shown that the frequency of CPM is higher among women with a family history of breast cancer and among women undergoing genetic testing even if they test negative for a mutation in BRCA1/2." (PMID 27650678, 2016). "Higher BRCA1 mutation frequency was observed in early-onset breast cancer patients regardless of family history of breast/ovarian cancer (28.2 % vs. 11 %, P = 0.0003)." (PMID 27553291, 2016). "Focusing on breast cancer, 9.7% (320/3,315) of female breast cancer patients without prior BRCA1/2 testing were found to carry a pathogenic or likely pathogenic variant." (PMID 26681312, 2016).
breast cancer (continued). "According to recent results, assessment of presence or absence of mentioned alleles in BRCA1 microsatellite can be used for prognosis in individuals, suspected of having or not having the breast cancer." (PMID 27351029, 2016). "This paves way for further xenograft experiments with BRCA1-defective breast cancer cell lines which could bring out the specific and pronounced effects of PB in BRCA1-defective BCSCs as is expected from the in vitro and in vivo data generated from this study." (PMID 27229859, 2016). "The correlation between BRCA1 and FOXO3 expression in the panel of breast cancer cell lines led us hypothesize that BRCA1 regulates FOXO3 expression." (PMID 27043660, 2016). "Despite the low number of patients in this study, it could be concluded that mutations in BRCA1 and BRCA2 occur in male breast cancer patients of luminal A subtype." (PMID 27478808, 2016). "The function of BARD1 in the body’s response to breast cancer remains relatively unknown other than that it is present in the nucleus with BRCA1 during DNA repair." (PMID 30460281, 2016). "From genetically derived cancers (estimated to account for some 5 to 10 % of all cancers) only about 1 % represents gastric carcinomas, 3–5 % for colorectal cancers, and about 8 % for breast cancers (breast cancer 1, early onset = BRCA1 or breast cancer 2, early onset = BRCA2)." (PMID 27053248, 2016). "To establish the functional significance of BRCA1–FOXO3 regulatory axis in breast cancer, we evaluated whether the anti-proliferative function of BRCA1 is mediated through FOXO3." (PMID 27043660, 2016). "In addition, sequencing results illustrate significant decreased expression of the Nusap1 gene, which has been shown to regulate levels of BRCA1, an extensively studied tumour suppressor gene involved in double strand breaks and breast cancer." (PMID 27014724, 2016). "Finally our in silico expression correlation analysis suggests the existence of the BRCA1/NEAT1/miR-129-5p axis in breast cancer." (PMID 27556296, 2016). "The associations are even stronger when only specific-cancer genes are considered: all specific-cancer genes in the DSBR class are associated with estrogen-related tissues (CHEK2, breast cancer; RAD51C and RAD51D, ovary cancer; and the DSBR cancer gene BRCA1, breast and ovary)." (PMID 26856619, 2016). "Family history of breast cancer is considered to be an important risk factor for developing CBC even among women without mutations in the BRCA1/2 breast cancer susceptibility gene." (PMID 27650678, 2016). "Together, our findings suggest a tumor-suppressive function of miR-342 that could be exploited in the treatment of a subset of BRCA1-mutant hereditary breast cancers." (PMID 26919240, 2016). "To investigate this, we engrafted BRCA1-mutant 69 mouse breast cancer cells in athymic nude mice." (PMID 27806319, 2016). "Compared to non-carriers, BRCA1-associated breast cancers (BCs) are often high-grade and poorly differentiated infiltrating ductal carcinomas with special immunophenotypic features." (PMID 27659521, 2016). "Moreover, we found that NEAT1 upregulation is required for the BRCA1-deficiency-driven effect on increasing the EpCAM+BCSC population and enhancing malignancies of breast cancer cells." (PMID 27556296, 2016). "If BRCA1 is damaged by a mutation, damaged DNA is not repaired properly, and this increases the risk for breast cancer." (PMID 26840090, 2016). "Utilizing SYBR Green based real-time allele-specific PCR, we have analyzed DNA samples of patients with breast cancer and disease free controls to identify the following BRCA1 and BRCA2 mutations: BRCA1 5382insC, BRCA1 4153delA, BRCA1 185delAG, BRCA1 300T>G, BRCA2 6174delT." (PMID 29138730, 2016). "In breast cancer, BRCA-1, a tumor suppressor gene, has been shown to play a role in protecting against ROS damage; BRCA-1 mutations have subsequently been implicated in loss of redox balance with increased ROS, and may potentially drive cancer development." (PMID 27431913, 2016).